TYMP (thymidine phosphorylase)
Diseases named in the same sentence as TYMP in open-access papers (continued):
Sharing a sentence is not in itself a finding about the gene and the disease.
tumor (continued). "The highly expressed thymidine phosphorylase in tumor tissue can degrade it into 5-FU, significantly increasing the drug concentration at the tumor site, and simulating continuous perfusion of 5-FU, so that it maintains a stable blood drug concentration at the action site." (PMID 40258007, 2025). "Moreover, TYMP not only promotes tumor progression but also influences normal physiological functions, making it crucial to consider the potential side effects of TYMP-targeted therapies." (PMID 40303404, 2025). "Notably, TYMP expression was significantly higher in malignant epithelial cells, suggesting a critical role for TYMP in tumour cells." (PMID 39548315, 2025). "Several studies showed that TYMP may play an important role in tumor development by promoting tumor angiogenesis." (PMID 39023413, 2024). "Thymidine phosphorylase (TP) at the tumor site then finally converts 5′-DFUR to 5-FU." (PMID 38748229, 2024). "Finally, 5'-DFUR is metabolized to 5-FU by thymidine phosphorylase (TP), which is highly expressed in tumor tissue." (PMID 39534818, 2024). "TYMP is expressed not only in the tumor epithelial cells but also in macrophages." (PMID 35567733, 2022). "Thymidine phosphorylase, expressed in largeamounts in tumor tissues, is also found in high concentrations in the palms of thehands and soles of the feet which, when found in these regions, could explain theclinical presentation of HFS." (PMID 36043574, 2022). "TYMP (thymidine phosphorylase), a nucleoside metabolism enzyme that catalyzes the conversion of thymidine to thymine and 2-deoxyribose-1-phosphate, plays an important role in tumor angiogenesis, apoptosis, and cell proliferation." (PMID 35265561, 2022). "Next, to assess the clinical significance of TYMP in DC monotherapy, TYMP expression in CT-26 tumor tissues was compared and correlated (multivariate correlation analysis) with the number of CD31+ and CD8+-PD1+ cells among TILs and the mean survival among different groups." (PMID 36090972, 2022). "Capecitabine is an orally available prodrug that is activated through a three-step enzymatic metabolic process, initially to 5′-deoxy-5-flu- orocytidine (5′-DFCR), then to 5′-deoxy- 5-fluorouridine (5′-DFUR), and finally to 5-FU by thymidine phosphorylase in tumor tissue." (PMID 36578549, 2022). "TYMP is responsible for systemic tumor-specific CD8+ cell exhaustion and abrogates adoptive dendritic cell therapy efficacy in a preclinical CRC model, which depicts systemic T-cell loss and reduced ACT or immunotherapy efficacy observed in animal models with advanced CRC." (PMID 36090972, 2022). "Furthermore, analysis of TYMP and CD31 expression in tumor tissues indicated a significant reduction in TYMP-dependent neoangiogenesis." (PMID 36090972, 2022). "The ability of inhibiting neovascularization of TYMP inhibitor may determine the tumor suppression effect." (PMID 35314790, 2022). "The prognostic impact of the expression CD163, a receptor associated with TAM, and TYMP in stroma, respectively, tumor tissue is not yet established." (PMID 35567733, 2022). "In the tumour microenvironment, genes encoding tumour-related macrophage activities, such as the LYZ (lysozyme), TYMP (thymidine phosphorylase), and CD68 (pan-macrophage) genes, may affect the NLR." (PMID 34997351, 2022). "It is poorly understood whether TYMP overexpression in tumor tissues contributes to cancer mortality by compromising systemic antitumor immunity and limiting cell therapy efficacy." (PMID 36090972, 2022). "In addition, TYMP promotes tumor growth and metastasis by preventing apoptosis and inducing angiogenesis." (PMID 34454516, 2021). "Interestingly, the expression pattern of ABCC5 in individual tumours closely followed that of TYMP and TK1." (PMID 34132895, 2021). "Furthermore, a positive correlation was found between tumour expression of TYMP and TK1 (r = 0.77, p = 0.0013)." (PMID 34132895, 2021).
tumor (continued). "According to Yang, the Thymidine Phosphorylase might be expressed in macrophages of the tumor stroma, that can release angiogenetic factors with paracrine and autocrine mechanism." (PMID 31709268, 2019). "Therefore, medicinal chemists have tried to synthesize novel inhibitors of thymidine phosphorylase which have the potential to overcome the formation of new blood vessels and arrest the growth of tumor cells." (PMID 30871147, 2019). "Thymidine phosphorylase (TP; EC 2.4.2.4) is involved regulation of intra- or extracellular thymidine concentration, angiogenesis, cancer chemotherapy, radiotherapy, as well as tumor imaging." (PMID 30138393, 2018). "This study also underlines the need for a more detailed investigation of the determinants of thymidine metabolism, such as the expression and activity of the enzymes TK1, thymidine phosphorylase and thymidylate synthase, in a similarly wide range of tumour models." (PMID 27515446, 2016). "TYMP expression was measured on tumor sections by immunohistochemical analysis." (PMID 27283904, 2016). "Capecitabine converts into 5-FU via thymidine phosphorylase (TP) in the tumor." (PMID 27577082, 2016). "The effects could be explained by capecitabine's synergistic effect with cytotoxic drugs through increased thymidine phosphorylase levels in tumours." (PMID 26420815, 2015). "Furthermore, tumor tissues from the established Bel-7402 mouse model had consistently high expression of TYMP and TK1 by IHC analysis, whereas the mouse normal liver tissue showed only basal level of either protein (panels F-H versus panels E)." (PMID 25881156, 2015). "In addition, TAS-102 reported encouraging results compared with placebo in randomized phase-III study, which is a new oral nucleoside anti-tumour agent consisting of trifluorothymidine and a thymidine phosphorylase inhibitor." (PMID 26311588, 2015). "Moreover, induced high level of TYMP has been found in tumor tissues due to inflammatory infiltration or after radiotherapeutic treatment and chemotherapy such as paclitaxel, doxorubicin and oxaliplatin." (PMID 25881156, 2015). "Of them, thymidine phosphorylase, E3 ubiquitin-protein ligase, and tumor protein D52 are involved in processes of angiogenesis, tumor growth, or metastasis and the rest are proteins with different physiological functions and no reported involvement in cancer development or progression." (PMID 25215235, 2014). "Thymidine phosphorylase may be overexpressed in both neoplastic cells and tumor stromal cells in a variety of malignancies." (PMID 22162690, 2011). "Additionally, radiation can magnify the tumor selectivity of capecitabine by upregulating thymidine phosphorylase in the tumor cells." (PMID 20584299, 2010). "Capecitabine is an oral fluoropyrimidine that preferentially delivers 5-FU to the tumour via a three-step enzymatic conversion, the final step being catalysed by thymidine phosphorylase, which has a higher activity within the tumour compared with healthy tissue." (PMID 16552436, 2006). "Thymidine phosphorylase levels might be increased secondary to the microenvironmental changes that accompany tumour growth and invasion." (PMID 15841086, 2005). "Capecitabine (X) is an oral fluoropyrimidine, which is absorbed from the gastrointestinal tract as an intact molecule, metabolised primarily in the liver and converted in tumour tissues to 5FU by the enzyme thymidine phosphorylase (found in higher concentrations in tumour cells than normal cells)." (PMID 15928658, 2005). "In addition, the thymidine phosphorylase inhibitor (TPI) has been shown to reduce both tumour invasion and distant metastasis of a TP-expressing solid tumour in a mouse model." (PMID 15841086, 2005). "In the tumour, the activity of thymidine phosphorylase may be critical, because this enzyme plays a double role in the activation of capecitabine." (PMID 12618890, 2003).
tumor (continued). "Capecitabine (Xeloda®) is a tumour-selective fluoropyrimidine carbamate designed to mimic continuous infusion 5-FU and to generate 5-FU preferentially in tumour tissue by exploiting the higher concentrations of thymidine phosphorylase (TP) found in malignant cells compared with normal cells." (PMID 11986765, 2002). "Furthermore, it is converted by thymidine phosphorylase to 5-FU in tumor tissue." (PMID 24428956, 2014). "We analyzed the role of ICDRs in tumor immune microenvironment by using the previous data of single cell transcriptome, and we analyzed the distribution of several key genes (PSME2, TYMP, KLHDC7B, GBP5, EPSTI1, STAT1 and OAS2) in different cell types." (PMID 40259929, 2025). "Analytical results revealed TYMP and HS3ST2 in tumor samples were significantly upregulated and GCNT4 and FUT3 were significantly downregulated." (PMID 41155476, 2025). "TYMP and GCNT4 were experimentally validated as key genes, functioning as oncogenic and tumor-suppressive factors." (PMID 41155476, 2025). "In TAS102-treated tumours, TYMP and Ki67 staining decreased, and caspase 3 increased, demonstrating that TAS102 effectively inhibited tumour growth and induced apoptosis." (PMID 39548315, 2025). "Apart from liver, this reaction takes also place in cancer cells; TYMP expression is higher in tumor cells compared to healthy tissue, leading to CAP preferential activation in tumor cells." (PMID 37256234, 2023). "TAS-102 selectively targets thymidine phosphorylase (TP), which functions synergistically with anti-VEGF-targeted treatment to prevent tumor angiogenesis." (PMID 38202064, 2023). "The rationale for combined therapy is that TPI downregulates TYMP and turns tumor cells immunogenic via induction of immunogenic cell death (ICD) to present tumor antigens to DCs to recruit T cells and modulate tumor-infiltrating lymphocytes (TILs)." (PMID 36090972, 2022). "In this study, we analyzed TYMP and CD163 expression in micro- and macrodissected tumor tissue from 312 patients with stage II CRC." (PMID 35567733, 2022). "The results showed a positive correlation between TYMP and CD163 gene expression, both in macro- and microdissected tumor tissue." (PMID 35567733, 2022). "Here, we tested the immunomodulatory effects of the TYMP inhibitor tipiracil hydrochloride (TPI), alone and in combination with a TLR7 agonist (imiquimod), activated whole tumor lysate-pulsed DCs (IMQDC-Ag), both in vitro and in vivo." (PMID 36090972, 2022). "Overall, these data show that IFNγ and TNFα secreted from T cells during TDCC can induce TYMP gene transcription followed by TP protein synthesis in MKN45, which efficiently converts capecitabine to 5′-FU at the tumour site." (PMID 36071036, 2022). "Gene expression of TYMP and CD163 was analyzed in snap-frozen tumor tissues and in microdissected formalin-fixed tumor tissues separated into tumor epithelium and stroma." (PMID 35567733, 2022). "We noticed that the mRNA expressions of FPB1 and HDAH were negatively correlated with tumor grade in patients with KIRC, while that of TYMP was positively correlated." (PMID 35250999, 2022). "The active form, 5-FU, is obtained by thymidine phosphorylase metabolization of 5-DFUR, mostly inside the tumor." (PMID 34647142, 2021). "Meanwhile, RT-qPCR assays revealed that ALDH6A1, FBP1, HAO2 and PSAT1 were markedly under-expressed in tumor tissues in exceeding 60% cases, and that TYMP, HK3, P4HA3, IL4I1, CYP26A1 and CPT1B were over-expressed in tumor tissues in exceeding 70% cases." (PMID 32737333, 2020). "In contrast, TYMP and TK1 positive staining were overwhelmingly observed in the tumor tissues, suggesting that Bel-7402 cell line indeed represented such a subtype of liver tumors." (PMID 25881156, 2015). "Normal human liver tissue showed only low basal levels of TYMP and TK1 protein expression as compared to those of tumor samples (panel A versus B)." (PMID 25881156, 2015).
tumor (continued). "Although many genes were downregulated in GB-1 3D culture relative to the parental tumor (e.g. FGFR3, TGFβ1 and TYMP), certain genes were now upregulated (e.g. FGF2, ANGPT1 and EFNA3)." (PMID 26203665, 2015). "Capecitabine is converted by carboxylesterase in the liver to 5′-deoxy-5-fluorocytidine (5′-DFCR), by cytidine deaminase in the liver and tumor tissue to 5′-deoxy-5-fluorouridine (5′-DFUR), and by thymidine phosphorylase (TP) to 5-FU in tumor tissue." (PMID 23822606, 2013). "There was a significant inverse correlation between the tumour VMI and nodal status (Fisher's exact test, P = 0.01) and between high VMI and low thymidine phosphorylase (TP) expression (Mann–Whitney U -test, P = 0.01)." (PMID 10732757, 2000). "To further explore the role of TYMP, we analysed its gene expression from scRNA-seq data and found that TYMP was differentially expressed in epithelial cells, which are much more prevalent in tumours with non-immune subtypes compared to immune subtypes." (PMID 39548315, 2025). "To evaluate the drug efficacy in non-immune subtype tumours, we selected a non-immune tumour with high TYMP expression (tumour#Exp031854) and established a patient-derived xenograft (PDX) model." (PMID 39548315, 2025). "Thus, TYMP can prevent cell apoptosis by activating the PI3K/Akt pathway, supporting tumor cells in resisting apoptosis induced by various treatments such as the immune response, hypoxia, radiotherapy, and chemotherapy." (PMID 40303404, 2025). "TYMP is highly expressed not only in tumor cells but also in normal cells, including macrophages, stromal cells, glial cells, and certain epithelial cells." (PMID 40303404, 2025). "TYMP, which was found to be highly expressed in tumour tissues, especially in non-immune subtypes, and exhibited a significant negative association with the prognosis in HGSC patients of non-immune subtypes in both Xiangya and CPTAC 2016 cohort." (PMID 39548315, 2025). "Furthermore, cell–cell communication analysis showed enhanced interactions between TYMP+ TAMs and CD8+ T cells, endothelial cells, and fibroblasts, indicating a potential role in reshaping the immune landscape and promoting tumor progression." (PMID 40908584, 2025). "ERY974 increases capecitabine-induced cytotoxicity by promoting capecitabine conversion to its active form by inducing thymidine phosphorylase expression in non-inflamed MKN45 tumour through ERY974-induced IFNγ and TNFα in T cells." (PMID 36071036, 2022). "Another TYMP inhibitor 5′-O-Trityl-inosine (Kin59) also shows antiangiogenic effect in vitro, but there is a lack of anti-tumor effect of kin59 in vivo." (PMID 35314790, 2022). "Combined, this evidence and the multivariate correlation analysis of the studied factors suggest that targeting TYMP with TPI does not significantly prolong the survival of CT-26 tumor-bearing animals but induces ICD at all in vivo doses of TPI tested." (PMID 36090972, 2022). "Among the 20 cancer types in TCGA, the expression of TYMP was elevated in 75% (15/20) of tumor tissues relative to normal controls." (PMID 35250999, 2022). "Paracrine stimuli, such as thymidine phosphorylase (TP) and vascular endothelial growth factor (VEGF), released from cancer cells, stromal cells and activated macrophages play an important role in the regulation of tumour angiogenesis." (PMID 11986782, 2002). "Thus, the effect of TYMP and CD163 gene expression on CRC carcinogenesis may vary depending on whether these genes are mostly expressed in tumor epithelial or stromal cells." (PMID 35567733, 2022). "To investigate the potential correlations between TYMP and neoangiogenesis and CD8+/PD1+ presence in immune infiltrate CT-26 tumors, we performed immunohistochemical localization of TYMP, CD31, and CD8/PD1 in tumor tissue and performed multivariate correlation analysis." (PMID 36090972, 2022).
tumor (continued). "In addition, we found that TYMP significantly correlated with PECAM1, an indicator of microvascular density that was up-regulated in the PME, and positively correlated with tumor size and prognosis." (PMID 35314790, 2022). "Although the antiangiogenesis effect of Kin59 is not as significant as that of TPI, it still showed anti-tumor effect, which may be related to the effect of TYMP inhibition of Kin59." (PMID 35314790, 2022). "However, the results did not correlate to the progressive levels of TK1 in tumor tissues, suggesting a complicated mechanism, possibly involving catabolism by TYMP." (PMID 25881156, 2015). "Capecitabine is an oral prodrug of fluorouracil, which is converted into the active substance 5-fluorouracil (5-FU) by the higher level of thymidine phosphorylase (TP) in the tumor, it may provide better efficacy and safety due to non-cytotoxic of capecitabine and its intermediates." (PMID 34867401, 2021). "Indeed, we verified that in particular TYMP and the Ecto-5′-nucleotidase NT5E constitute crossing points with angiogenesis and thus their unbalanced expression in GC may lead to an improved tumor vascular formation or to the stimulation of the vasculogenic mimicry process." (PMID 32887417, 2020).